IGHD1-1 (immunoglobulin heavy diversity 1-1)
Description:
D region of the variable domain of immunoglobulin heavy chains that participates in the antigen recognition. Immunoglobulins, also known as antibodies, are membrane-bound or secreted glycoproteins produced by B lymphocytes. In the recognition phase of humoral immunity, the membrane-bound immunoglobulins serve as receptors which, upon binding of a specific antigen, trigger the clonal expansion and differentiation of B lymphocytes into immunoglobulins-secreting plasma cells. Secreted immunoglobulins mediate the effector phase of humoral immunity, which results in the elimination of bound antigens. The antigen binding site is formed by the variable domain of one heavy chain, together with that of its associated light chain. Thus, each immunoglobulin has two antigen binding sites with remarkable affinity for a particular antigen. The variable domains are assembled by a process called V-(D)-J rearrangement and can then be subjected to somatic hypermutations which, after exposure to antigen and selection, allow affinity maturation for a particular antigen.
Synonyms: IGHD11
Tractability: Antibody: UniProt places it where antibodies can reach, with medium confidence; its Gene Ontology location is reachable by antibodies, with medium confidence.
Gene: Immunoglobulin diversity (D) gene on chromosome 14 (105,919,502 to 105,919,518, reverse strand). Ensembl gene ENSG00000236170.
Subcellular location: Secreted; Cell membrane
Gene Ontology:
Cellular component: extracellular region; plasma membrane